ANXA2 (annexin A2)
Diseases named in the same sentence as ANXA2 in open-access papers (continued):
Sharing a sentence is not in itself a finding about the gene and the disease.
head and neck cancer (3 papers, 2013 to 2018). A primary or metastatic malignant neoplasm affecting the head and neck. "A meta-analysis of 2321 cancer patients with several cancer types including head and neck cancers (esophageal, sinonasal, and oral), showed that a high expression level of Annexin A2 (ANXA2) was related to poor overall survival and disease-free survival." (PMID 29598816, 2018). "The level of ANXA2 mRNA expression is relatively high in the cervical and head/neck cancers which are largely correlated with HPV infection, whereas ANXA4 mRNA expression showed intermediate level in the both cancers." (PMID 27402115, 2016).
inflammatory bowel disease (3 papers, 2017 to 2025). A spectrum of small and large bowel inflammatory diseases of unknown etiology. "Compelling evidence also supports the critical role of ANXA2 in inflammatory myopathies and in inflammatory bowel disease." (PMID 28848713, 2017).
injury (3 papers, 2019 to 2025). Damage inflicted on the body as the direct or indirect result of an external force, with or without disruption of structural continuity. "Treatment with AAV8-shRNA-Anxa2 did not affect Anxa2 expression in leukocytes (CD45+), mesenchymal cells and endothelial cells during APAP-induced mouse liver injury compared with control." (PMID 38693268, 2024).
ischemia (3 papers, 2009 to 2024). A hypoperfusion of the BLOOD through an organ or tissue caused by a PATHOLOGIC CONSTRICTION or obstruction of its BLOOD VESSELS, or an absence of BLOOD CIRCULATION. "The effect of Annexin A2 on retinal neovascularization were assayed by siRNA interference and overexpression of Annexin A2, fluorescence imaging, and immunofluorescence histochemistry in a mouse model of ischemia-induced retinal neovascularization." (PMID 19536308, 2009). "We investigated the effect of vascular endothelial growth factor (VEGF) on annexin A2 expression and related intracellular signaling mechanisms in a mouse model of ischemia-induced retinal neovascularization." (PMID 19536308, 2009). "Expression of annexin A2 mRNA and protein were increased in the mouse model of ischemia-induced retinal neovascularization and in RF/6A cells treated with VEGF." (PMID 19536308, 2009). "Here we describe a preliminary investigation of the expression of annexin A2, its effect on angiogenesis, and its functional relationship with VEGF in a mouse model of ischemia-induced retinal neovascularization model and in RF/6A cells." (PMID 19536308, 2009).
kidney cancer (3 papers, 2009 to 2022). Primary or metastatic malignant neoplasm involving the kidney. "High expression of annexin A2 was clearly observed in human squamous cell lung cancer and kidney cancer tissue." (PMID 25641213, 2015).
liver cirrhosis (3 papers, 2013 to 2025). "In conclusion, the expression of serum and tissue ANXA2 was not only elevated in the patients with HBV-related HCC but also in the patients with liver cirrhosis." (PMID 23946789, 2013). "Healthy controls were not immunostained while the number of cases immunoreactive for ANXA2 steadily increased from the liver cirrhosis tissues (20/39, 51.3%) to the non-cancer (53/87, 60.9%) and cancer (68/87, 78.2%) tissues." (PMID 23946789, 2013). "The cancer tissues exhibited a significantly higher ANXA2-positive rate than the non-cancer (P=0.013) and liver cirrhosis tissues (P=0.002)." (PMID 23946789, 2013). "The cancer tissues exhibited a significantly higher ANXA2-positive rate compared with the non-cancer (P=0.013) and liver cirrhosis tissues (P=0.002)." (PMID 23946789, 2013). "However, the prognostic value of ANXA2 in Taiwanese HCC patients remains unclear, where a great proportion of patients had chronic hepatitis B with liver cirrhosis." (PMID 34575275, 2021). "Furthermore, marked ANXA2 staining was more prevalent in the cancer tissues (16/87, 18.4%) than the non-cancer (4/87, 4.6%; P=0.004) and liver cirrhosis (1/39, 2.6%; P=0.034) tissues." (PMID 23946789, 2013). "Notably, HBV-miR-2 activated genes including inflammatory genes like P2RX7 and PYCARD, fibrosis-induced genes like ANXA2 and MIF oncogenic genes like FOS and JUN, which were further verified via RT-qPCR and highly expressed in the particular stages of CHB, liver cirrhosis and HCC." (PMID 40405227, 2025). "However, another study indicated that expression levels of ANXA2 in HCC tissue and serum specimens were not correlated well with clinical outcomes, suggesting that ANXA2 was not a good prognostic maker for HCC patients with HBV-related liver cirrhosis." (PMID 34575275, 2021).
lung disease (3 papers, 2020 to 2022). "Additional mechanistic evidence comes from a study that showed bleomycin directly binds to annexin A2 (ANXA2) in lung epithelial cells, thereby preventing the nuclear translocation of TFEB; thus, there is an inhibition of the autophagy flux resulting in fibrotic lung disease pathogenesis." (PMID 32847034, 2020).
malignant glioma (3 papers, 2017 to 2021). A grade III or grade IV glioma arising from the central nervous system. "Annexin A2 (ANXA2) is a candidate biomarker for malignant gliomas that was additionally identified to be directly involved in angiogenesis-dependent invasion through the up-regulation of the vascular endothelial growth factor (VEGF)." (PMID 31357616, 2019). "Anti-tumor compound, Chlorotoxin (CTX) and TM601, have been proved to be bound with cell surface ANXA2 in malignant gliomas." (PMID 29291003, 2017).
mastitis (3 papers, 2019 to 2024). Inflammation of breast tissue during lactation or postpartum due to an obstructed duct or infection. "It is suggested that targeting the association between ClfB and AnxA2 might confer protection against S. aureus mastitis in dairy cattle." (PMID 34683411, 2021). "Blocking the functionality of ClfB by natural plant extracts can potentially have a significant impact on the S. aureus virulence as it has been previously shown that ClfB can bind to AnxA2 and offer protection against mastitis." (PMID 38414081, 2024). "These implicate a potential role for ANXA2 in immunity and inhibition of inflammation during mastitis, but the specific regulatory role still needs further exploration." (PMID 31159303, 2019). "Targeting the interaction of ClfB and AnxA2 may confer protection against S. aureus mastitis." (PMID 34683411, 2021).
nephrocalcinosis (3 papers, 2018 to 2025). Nephrocalcinosis is a disorder that occurs when too much calcium is deposited in the kidneys. "ANXA2 mediates the binding of calcium oxalate crystals to renal epithelial cells and is involved in the pathogenesis of nephrolithiasis and nephrocalcinosis." (PMID 36120574, 2022). "Therefore, ANXA2 may mediate adhesion of the crystals to tubular epithelial cells, promote crystal retention and finally contribute to the pathogenesis of nephrolithiasis and nephrocalcinosis." (PMID 36120574, 2022).
oral cancer (3 papers, 2013 to 2025). "Additionally, down-regulation of cytoskeletal proteins, including SH3GLB2 (endophilin-B2), spectrin (SPTAN1), and annexin (ANXA2) in T2D individuals mirrors the pattern seen in oral cancers and precancerous lesions." (PMID 39794871, 2025). "LUCAT1 promotes cell invasion in several cancer types, including gastric, liver, and oral cancer cells, by modulating YWHAZ, Annexin A2, or PCNA." (PMID 36980216, 2023).
prostate tumors (3 papers, 2010 to 2020). "Another example used gene delivery to achieve apoptosis in prostate tumors by delivering pDNA expressing an shRNA against annexin A2." (PMID 22506124, 2012). "Intratumoral administration of pDNA-shAnxA2-loaded NP to xenograft prostate tumors in nude mice inhibited tumor growth through reductions in annexin A2 and VEGF levels." (PMID 22506124, 2012).
Salmonella Infections (3 papers, 2021 to 2024). Infections with bacteria of the genus SALMONELLA. "To further assess AnxA2’s involvement in SopD2-mediated phenotypes during Salmonella infection, we did a knockdown of AnxA2 in HeLa cells using shRNA mediated RNA interference." (PMID 34880286, 2021).
sarcoidosis (3 papers, 2024 to 2025). Sarcoidosis is a multisystemic disorder of unknown cause characterized by the formation of immune granulomas in involved organs. "In addition, ANXA2 is found on macrophages, as a cytoplasmic and cell surface molecule that is involved in endocytosis, a pathway frequently found associated with sarcoidosis; however the exact role of this gene in sarcoidosis and/or progression is unclear at this time and will require future study." (PMID 39080656, 2024). "DNAm and mRNA association analyses both identified differential regulation of the gene ANXA2, which displays hypomethylation and increased gene expression in sarcoidosis samples." (PMID 39080656, 2024). "ANXA2 protein levels have previously been reported to be increased in BALF from sarcoidosis cases." (PMID 39080656, 2024).
sickle cell disease (3 papers, 2021 to 2024). Sickle cell anemias are chronic hemolytic diseases that may induce three types of acute accidents: severe anemia, severe bacterial infections, and ischemic vasoocclusive accidents (VOA) caused by sickle-shaped red blood cells obstructing small blood vessels and capillaries. "The results indicate that the polymorphisms in BMP6, Klotho and ANXA2 genes may be associated with avascular necrosis in patients with sickle cell disease." (PMID 35584416, 2022). "The results indicate that polymorphisms in the genes of the bone morphogenetic protein 6 (BMP6), Klotho (KL) and Annexin A2 (ANXA2) may be associated with osteonecrosis in the context of sickle cell disease." (PMID 35584416, 2022). "Furthermore, the Cooperative Study of Sickle Cell Disease (CSSCD) DNA samples have identified certain candidate gene SNPs (e.g., BMP6, annexin A2, and klotho) as risk factors for the development of avascular necrosis of the hip and/or shoulder." (PMID 39113817, 2024).
squamous cell carcinoma (3 papers, 2013 to 2016). A carcinoma arising from squamous epithelial cells. "ANXA2 was more highly expressed in squamous cell carcinoma, whereas ANXA4 was expressed more prominently in adeno-/adenosquamous carcinoma (p < 0.001 and p < 0.001, respectively)." (PMID 27402115, 2016). "ANXA2 expression was more prominent in squamous cell carcinoma (p < 0.001), whereas ANXA4 was more highly expressed in adeno/adenosquamous carcinoma (p < 0.001)." (PMID 27402115, 2016). "Moreover, annexin A2 isoforms and cleaved annexin A2 were observed in normal and squamous cell carcinoma tissues, confirmed by 2D-western immunoblotting." (PMID 23945256, 2013).
systemic lupus erythematosus (3 papers, 2023 to 2026). An autoimmune multi-organ disease typically associated with vasculopathy and autoantibody production. "The absence of ANXA2 affects tissue-type plasminogen activator (tPA)-dependent plasmin generation on endothelial cell surfaces, which may contribute to cerebral venous thrombosis and systemic lupus erythematosus, leading to thrombus formation." (PMID 40487068, 2025).
venous thromboembolism (3 papers, 2021 to 2025). Occlusion of the lumen of a vein by a thrombus that has migrated from a distal site via the blood stream. "Conversely, reduced AnxA2 levels disrupt cell surface fibrinolysis, increasing the risk of venous thromboembolism." (PMID 40943516, 2025). "Recent evidence suggests that decreased plasma fibrinolysis is a risk factor for venous thromboembolism, and that cell surface tPA receptor, especially AnxA2 is involved in this hypofibrinolysis." (PMID 34681689, 2021).
adenoma (2 papers, 2024). A neoplasm arising from the epithelium. "The expression of ANXA2 in adenomas, even in the high-grade dysplastic ones, was still lower than in CRC." (PMID 39594718, 2024). "The ANXA2 protein appears to be expressed in all three cell types (main, clear and oxyphil) of parathyroid cells, and immunohistochemical testing revealed a positive staining reaction in adenomas." (PMID 39064529, 2024). "They found that ANXA2 expression was increased in adenomas with high-grade dysplasia, especially of the tubulovillous type, suggesting that it may be involved in the early stages of CRC oncogenesis." (PMID 39594718, 2024).
Autoimmunity (2 papers, 2019 to 2020). The occurrence of an immune reaction against the organism's own cells or tissues. "A previous model was presented to explain how annexin A2 may become immunogenic and contribute to autoimmunity." (PMID 33043033, 2020).
brain infarction (2 papers, 2018 to 2025). Tissue necrosis in any area of the brain, including the cerebral hemispheres, the cerebellum, and the brain stem. "Further tests showed that administration of AnxA2, AnxA5, AnxA6, or AnxA7 to the healthy mouse brain caused brain CaP deposition, as tested by the Alizarin Red S assay, in association with brain infarction, as detected by the TTC assay." (PMID 39820937, 2025).
chronic kidney disease (2 papers, 2022 to 2023). Impairment of the renal function secondary to chronic kidney damage persisting for three or more months. "Moreover, Anxa2 is a novel biomarker and potential therapeutic target with prognostic value in chronic kidney disease." (PMID 37955107, 2023). "Our studies have shown that tPA, a ligand of ANXA2, promotes kidney fibrosis and inflammation in the mice with unilateral ureteral obstruction (UUO), a classic chronic kidney disease mouse model." (PMID 36120574, 2022).
Coagulopathy (2 papers, 2021 to 2024). "Taken together, we demonstrated that AC70 hACE2 Tg mice lethally challenged with SARS-CoV-2 recapitulated several features of COVID-associated coagulopathy observed in patients and highlighted the potential role of ANXA2 in this phenomenon." (PMID 38913740, 2024). "We have also demonstrated that the fine balance between coagulation and fibrinolysis could be readily impaired and identified a possible role of Annexin A2 in coagulopathy developed after SARS-CoV-2 infection." (PMID 38913740, 2024). "Thus, an altered ANXA2-mediated fibrinolysis, in part due to enhanced induction of autoantibodies against ANXA2 triggered upon SARS-CoV-2 infection, might contribute to the complex pathophysiological mechanisms of COVID-associated coagulopathy." (PMID 38913740, 2024).
colorectal neoplasm (2 papers, 2010 to 2024). A benign or malignant neoplasm that affects the colon or rectum. "Annexin A2 has been extensively studied in the colorectum and has emerged as a significant factor in the oncogenesis and progression of human colorectal neoplasms, as well as a potentially valuable diagnostic and therapeutic tool." (PMID 39594718, 2024).
diabetic kidney disease (2 papers, 2024 to 2025). Progressive kidney disorder caused by vascular damage to the glomerular capillaries, in patients with diabetes mellitus. "In patients with diabetic kidney disease (DKD), expression of ANXA2 in the tubulointerstitium was significantly increased compared to healthy donor kidneys." (PMID 40889685, 2025).
diabetic retinopathy (2 papers, 2025). "In chronic inflammatory environments, ANXA2 facilitates sustained angiogenesis, which contributes to diseases like diabetic retinopathy." (PMID 40487068, 2025).
esophageal tumors (2 papers, 2024). "The following table summarizes existing research on the role of ANXA2 in esophageal tumors." (PMID 39594718, 2024).
fungal infection (2 papers, 2019 to 2021). "It has been reported that Anxa2-deficient mice exhibited enhanced inflammatory responses during fungal infection." (PMID 31159303, 2019). "Compromised fungal uptake, propagation and release, together with an enhanced inflammatory response, probably explains that Anxa2−/− mice died more rapidly than control animals after fungal infection." (PMID 33810523, 2021). "During fungal infection (Cryptococcus) of macrophages, AnxA2 controls phagocytosis and non-lytic exocytosis of the pathogen." (PMID 33810523, 2021).
glomerular diseases (2 papers, 2014 to 2025). "The alternative pathway is activated in patients with a diverse range of glomerular diseases, many of which are associated with increased local expression of AnxA2." (PMID 40889685, 2025). "We infer that ANXA1 and ANXA2 may play important pathogenic roles in glomerular disorders." (PMID 24591769, 2014). "We then examined ANXA1 and ANXA2 mRNA and protein expression in patients with various types of glomerular disorders by ISH or IHC staining." (PMID 24591769, 2014). "However, the expression patterns and potential roles of ANXA1 and ANXA2 remain unclear in most glomerular disorders." (PMID 24591769, 2014). "In the present study, we characterized the expression pattern and tissue distribution of ANXA1 and ANXA2 in the ADG model over time and confirmed these results in a large number of different types of human glomerular disorders." (PMID 24591769, 2014).
Hepatitis (2 papers, 2020 to 2021). Inflammation of the liver. "Fourth, a previous study reported that ANXA2 could be secreted to the extracellular environment upon interferon-γ treatment, suggesting that hepatitis activities might play a role." (PMID 34575275, 2021).
hepatopulmonary syndrome (2 papers, 2021). Hepatopulmonary syndrome (HPS) is a lung disease characterized by widening of arteries and veins (dilatation) in the lungs in people who have chronic liver disease. "Also, ANXA2 modulates pulmonary arterial smooth muscle cell proliferation for hepatopulmonary syndrome." (PMID 34109194, 2021). "The negative correlation between miR-206 and ANXA2 was identified in rats with hepatopulmonary syndrome." (PMID 34055578, 2021).
homocysteinemia (2 papers, 2021 to 2023). "Blockade of annexin A2 function in vivo, by gene ablation or by a diet leading to hyper-homocysteinemia, leads to loss of endothelial cell surface plasmin generation, reducing endothelial cell migratory capacity that leads to angiogenic failure." (PMID 33986681, 2021).
human papilloma virus infection (2 papers, 2012 to 2022). An infectious process caused by a human papillomavirus. "The blocking of the annexin A2 heterotetramer by SLPI inhibits the human papilloma virus infection." (PMID 36012891, 2022).
Hyperglycemia (2 papers, 2012 to 2021). An increased concentration of glucose in the blood. "Hyperglycemia also causes hyper-coagulation by increasing the levels of advanced glycation end-products modified forms of cellular and membrane AnxA2." (PMID 34681689, 2021). "Similarly, we hypothesize that the up-regulation of Annexin A2 in the placenta villi is a response to hyperglycemia or a prothrombotic milieu in GDM patients, playing a role to keep the fibrolysis balance in the placenta." (PMID 22970290, 2012).
idiopathic nephrotic syndrome (2 papers, 2023 to 2025). Nephrotic syndrome for which no cause has been identified. "For example, annexin A2 autoantibody was detected in 17.8% of children with MCD or FSGS, anti-actin and ATP- synthase – in 16.7% of children with idiopathic nephrotic syndrome." (PMID 37409273, 2023).
kidney inflammation (2 papers, 2015 to 2022). "Annexin A2 has been shown to act as a co-receptor of integrin CD11b mediating NF-kB-dependent kidney inflammation, which is further amplified through annexin A2/NF-kB-triggered macrophage M2 to M1 phenotypic change." (PMID 36120574, 2022).